EGF (epidermal growth factor)
Diseases named in the same sentence as EGF in open-access papers (continued):
Sharing a sentence is not in itself a finding about the gene and the disease.
tumor (continued). "Aeroplysinin-1 has been shown to display a strong anti-tumor effect on EGF-dependent tumor cell lines through its claimed inhibitory effect on the intrinsic protein tyrosine kinase activity of EGF-receptor kinase complex." (PMID 23383109, 2013). "DOK2 expression inhibited tumor formation and partially suppressed EGF-induced RAS activation in NCI-H1975 cells." (PMID 24255704, 2013). "Present results support the concept of tumor imaging by measuring EGF receptor levels using EGF-NIR probe." (PMID 23857061, 2013). "There are many cytokines secreted by aHSCs that are associated with tumor invasion and metastasis, ingcluding HGF, EGF, IL-1, IL-2, IL-6, MMP-2, MMP-9, TGF-β, TNF-α, VEGF and Wnt families." (PMID 23622143, 2013). "Numerous extracellular signaling molecules are implicated in promoting invasive tumor cell migration including hepatocyte growth factor (HGF), transforming growth factor β (TGF-β), epidermal growth factor (EGF), and lysophosphatidic acid (LPA)." (PMID 23527039, 2013). "Of interest was the fact that due to stimulation by TNFα + Estrogen + EGF, over 50% of the tumor cells acquired high expression levels of both β1 and CD44 together." (PMID 24369447, 2013). "Active migration of tumor cells is a prerequisite for tumor progression and metastasis and reports show that EGF-induced cancer cell migration can be inhibited by suppressing Cdc42/Rac1 signaling pathways." (PMID 24040362, 2013). "When doing this analysis, we were aware of the fact that MCF-7 cells are sensitive to TNFα cytotoxicity, and accordingly our routine procedure of TNFα + Estrogen + EGF stimulation for three days has led to death of approximately 40% of the tumor cells." (PMID 24369447, 2013). "Additional analyses indicated that the morphological changes induced by TNFα + Estrogen + EGF in the tumor cells were accompanied by redistribution of focal adhesion kinase (FAK) and paxillin, two key regulators of cell adhesion and spreading." (PMID 24369447, 2013). "The tumor cells were stimulated for three days by TNFα + Estrogen + EGF in vitro then washed to remove the stimulators and inoculated to the mammary fat pad of mice." (PMID 24369447, 2013). "Here, it is interesting to note that the single cells that migrated out of tumor-spheroids formed in the presence of TNFα + Estrogen + EGF stimulation expressed lower levels of E-cadherin compared to the cells that remained in the spheroids." (PMID 24369447, 2013). "Many tumor promotion agents, such as EGF, TPA, or ultraviolet, and transformation by oncogene H-ras or v-Src can elevate the level of phosphorylated histone H3 at Ser10." (PMID 23496845, 2013). "High expression of ITPKA has been reported to promote migration of tumor cells by two different mechanisms: ITPKA increases calcium entry that directly influences cell migration in EGF stimulated cells." (PMID 24564989, 2013). "hMena11a is also phosphorylated downstream of HER-2 and EGF (epidermal growth factor), and MenaINV facilitates invasion of tumor cells and their discohesive morphology." (PMID 23956979, 2013). "Previous reports have shown that TAMs contribute to tumor progression through secretion EGF and upregulation of the EGFR/Stat3/Sox-2 signaling pathway." (PMID 24312366, 2013). "Our findings support a key role for tissue hypoxia in eliciting angiogenic gene responses in CRC cells, also in combination with EGF, and highlight the complex interrelationship between tumour hypoxia, EGF and angiogenesis in the pathogenesis of CRC." (PMID 24180698, 2013). "Here, we showed increased cell migration in HT-29 cells that were treated with EGF, which confirms that EGF is a potential tumor promoter." (PMID 24069372, 2013). "The powerful spreading induced by TNFα + Estrogen + EGF has led us to monitor the expression of the β1 integrin, known to be strongly involved in processes of tumor cell adhesion, spreading, and metastasis formation." (PMID 24369447, 2013).
tumor (continued). "We have shown that increased cell migration is related to mechanisms of tumor progression in cancer cells and that EGF treatment increased the migration of Caco-2 cells." (PMID 24069372, 2013). "We calculated in the animal experiments and isolated tumor high SBRs of 4.8 ± 0.6 and 37 ± 7.4 for EGF-NIR binding, respectively." (PMID 23857061, 2013). "Neovasculature agent (RGD peptide), tumor stromal agent (matrix metalloproteinase), and tumor cell markers (epidermal growth factor, Her-2, interleukin 11) imaging agents were labeled with reporters." (PMID 23331017, 2013). "In respect to iNOS regulation, these central mediators also affect its expression, as macrophage EGF induces iNOS in tumor cells and tumor cell CSF-1 induces iNOS in macrophages." (PMID 23785333, 2013). "Mounting evidence supports a role for EGF in malignant transformation, tumor growth and progression." (PMID 23419149, 2013). "As the occurrence of EGFR on the tumor cells is critical for EGF-SubA toxin delivery, its presence was confirmed on the surface of all selected cell lines." (PMID 23887632, 2013). "To investigate the biological significance of EGF-induced IL-1β expression in tumor cells, we focused on drug resistance in cisplatin-induced apoptosis." (PMID 23383347, 2013). "Conversely, a high-level synergism was also observed, due to a strong and significant upregulation of numerous canonical EGF-targets with putative tumor-promoting properties such as MMP7, VEGFA, and IL-8." (PMID 23762360, 2013). "In conclusion, in the present study we show that it is possible to stimulate tumor cells by EGF, and thus enhance cell proliferation, resulting in a higher tumor growth compared to the untreated control group." (PMID 22825751, 2012). "Experimental tumor models suggest that cancer cells release factors such as CSF-1, which stimulates macrophages in the tumor microenvironment, with the subsequent release of EGF, which promotes proliferation of the tumor mass." (PMID 22481931, 2012). "This tool is of potential use for predicting and evaluating EGF responsiveness in patient-specific tumor therapy." (PMID 23028903, 2012). "The daily injection regime of EGF led to an enhanced tumor volume in both groups of mEGF- and hEGF-injected mice." (PMID 22825751, 2012). "We found that, in vitro, both Neu-YB and Neu-YD primary tumor cells had impaired wound healing to EGF compared to the Neu-NDL cells." (PMID 22314082, 2012). "Dysregulation of EGF and its receptors have been proved to promote tumor growth and metastasis of various types of cancer." (PMID 22701712, 2012). "Tumor-associated macrophages of the tolerogenic “M2” phenotype drive angiogenesis by secreting VEGF, MMP9, epidermal growth factor (EGF), and interleukin-8 (IL8)." (PMID 22312408, 2012). "We plan to extend this study to include additional tumor-targeting ligands including antibodies, proteins and small peptides such as epidermal growth factor (EGF) and TRAIL." (PMID 22891637, 2012). "We measured invasion by count of total cells that show chemotaxis and invade in the primary tumor toward a gradient source (EGF or FBS as a general chemoattractant source) with the in vivo invasion assay." (PMID 23113900, 2012). "The Neu-YD tumor cells were significantly less invasive to EGF compared to those of the Neu-YB and the Neu-NDL strains." (PMID 22314082, 2012). "At the molecular level, it has been found that HspB5-mediated growth of human breast basal-like tumor cells is epidermal growth factor (EGF)- and anchorage-independent." (PMID 24278676, 2012). "The EGFR-targeted MNT, after labeling with the residualizing [125I]SGMIB prosthetic group, bound to EGFR-expressing tumor cells with an affinity comparable to that of native EGF." (PMID 23107475, 2012). "Our results showed that EGF stimulation enhanced tumor volume, indicating that the application of extra EGF had a proliferative effect on tumor cells." (PMID 22825751, 2012).
tumor (continued). "Taken together the results serve as a basis for modeling the early cytoskeletal EGF response as a tightly coordinated and step-wise process which is relevant for the prediction of the effectiveness of anti-EGF receptor-based tumor therapy." (PMID 23028903, 2012). "To evaluate the effect of MSI1-KD on tumor cell colony formation in vitro, we performed methylcellulose gel colony-forming assays in the presence of EGF and FGF2." (PMID 22428049, 2012). "This indicates that invasion to EGF is dependent on CXCL12-CXCR4 signaling in the tumor microenvironment, specifically in the Neu-YB strain." (PMID 22314082, 2012). "Although the germline tumor phenotypes arising from EGF attenuation, Jak/STAT hyperactivation, or TGFβ hyperactivation are unique in certain aspects, they can all be classified as overproliferation phenotypes." (PMID 22586473, 2012). "In summary, the present study shows the role of the putative tumor migration suppressor VILIP-1 in counteracting the induction of EGF-induced EMT." (PMID 22479362, 2012). "EGF can inactivate GSK3β, leading to the degradation of c-Myc and β-catenin, which are overexpressed in tumour cells." (PMID 22343623, 2012). "This suggests that the CXCL12 expressed by the Neu-YB tumor cells was necessary for EGF induced in vivo invasion." (PMID 22314082, 2012). "In the present study, we show that it is possible to stimulate tumor cells in xenografts by EGF and thus, enhance cell proliferation, resulting in a higher tumor growth compared to the untreated control group." (PMID 22825751, 2012). "In other tumor models, EGF was shown to trigger an EMT with up-regulation of either SNAI1 or TWIST1 possibly through STAT3 activation." (PMID 22272264, 2012). "This will help to qualitatively and quantitatively assess EGF responsiveness of tumor cells at very high precision." (PMID 23028903, 2012). "The macrophages and tumor cells engage in a paracrine growth factor loop involving EGF and CSF1 to promote invasion in a mouse model of metastatic breast cancer." (PMID 22529912, 2012). "The EGF stimulated mice showed a significantly higher tumor growth compared to the serotonin-stimulated mice and the untreated controls." (PMID 22825751, 2012). "EGF-NIR imaging of mice with HT-29 orthotopic CRC tumor indicated that EGF-NIR is more slowly cleared from the tumor and the highest SBR between tumor and normal adjacent tissue was achieved two days post-injection." (PMID 23144978, 2012). "This EGF dependent-proliferation of spheroids emphasized the relevance of this model by comparison with cell monolayer and with tumor context." (PMID 22244109, 2012). "Further study revealed that the epidermal growth factor (EGF) released by TAMs interacted with the CSF-1 released by tumor cells to promote the migration of the tumor cells." (PMID 22778768, 2012). "In order to determine any relevant role of EGFR in mediating macrophage-stimulated tumor cell proliferation in these cell lines, recombinant mouse EGF was added at 2 ng/mL." (PMID 21699731, 2011). "Subsequent analysis of key nodes upstream of transcription factors predicted for transgenic and tumor promoter sets revealed a switch from EGF signaling in the pre-tumor state to IGF-2 in the tumor state." (PMID 21464922, 2011). "In order to summarize the results obtained in this study we have build a hypothetical model-diagram of the EGF/IGF-2 regulatory circuit functioning during the transition from transgenic to tumor state." (PMID 21464922, 2011). "The amount of EGFR expressed on S180 cells is likely to be abundant as a large amount of the EGF-SEA protein accumulated in the tumor site, peaking 62 hrs after i.v. injection." (PMID 21311755, 2011). "Using VeraTagTM technology, we developed and characterized quantitative assays measuring epidermal growth factor (EGF)-dependent increases in activated HER receptors in tumor cell line lysates and formalin-fixed, paraffin-embedded (FFPE) tumor sections." (PMID 21496232, 2011).
tumor (continued). "Taking into account the presence of EGF-receptors ErbB1-3 in both transgenic and tumor clusters, the networks reveal in addition how components of biological processes proposed by GO analysis were tied to EGF-signaling in the context of hepatocarcinogenesis." (PMID 21464922, 2011). "In the breast and uterus cancers, treatment with anti-EGF antibodies reduced tumor proliferation induced by treatment with estradiol." (PMID 22164169, 2011). "Our tumor and in vitro data strongly support a role for EGF modulation of Fas-induced cell death, probably through activation of CTGF." (PMID 22135505, 2011). "Together, we propose a switch in autocrine signaling to foster tumor growth that was initially triggered by EGF and demonstrate the knowledge gain form promoter analysis combined with upstream key node identification." (PMID 21464922, 2011). "Through the direct killing mediated by perforins and granzyme granules acting together with the apoptotic inducers, TNF-α and Fas, tumor cells were eliminated in EGF-SEA-treated mice, as demonstrated by TUNEL staining." (PMID 21311755, 2011). "Of note, a steeper correlation between HAS3 and EGFR levels was found in the subgroup of T = 1 tumours, which possibly suggests a stronger dependence of this early tumour stage on EGF stimulated HAS3 expression." (PMID 21429221, 2011). "In support of this, EGF-stimulation of tumor cells leads to phosphorylation of cortactin at serine residues 405 and 418 inducing a characteristic shift in cortactin electrophoretic mobility from 80 kDa to 85 kDa." (PMID 21886807, 2011). "Using electron microscopy, we observed that EGFR was readily detected in the mitochondria of EGF-treated tumor cells in which arrows mark gold particles that label EGFR." (PMID 21388543, 2011). "We observed that acute EGF/FGF addition to differentiated tumor cells reduces IR-induced γH2AX-signals while subacute and chronic withdrawal from non-differentiating stem-like cells increases them." (PMID 21663643, 2011). "During tumor cell invasion, elevated expression of EGF has been found to diffuse and generate a gradient of EGF receptor activation in adjacent cells, leading to an increase in tumor cell motility and invasiveness, thereby enhancing cancer cell metastasis." (PMID 21829671, 2011). "Tumor and in vitro data suggest viable cells counter the prodeath signal induced by FasL by activating EGF, which in turn induces prosurvival CTGF." (PMID 22135505, 2011). "Several reports have proposed a chemotactic and paracrine EGF/CSF-1 loop between macrophages and tumour cells, which allows them to work synergistically in an effort to co-migrate." (PMID 22005011, 2011). "Since activation of the EGFR pathway is associated with increased tumor aggressiveness and decreased survival in PDAC, we sought to determine the effect of EGF on motility." (PMID 22053213, 2011). "After digestion of tumor biopsies with collagenase and trypsin, cell suspensions were cultured in Mammary Epithelial Basal Medium supplemented with EGF, insulin, hydrocortisone, bovine pituitary extract (MEGM) and 1–2% FBS for up to 5 days." (PMID 21264259, 2011). "Other investigators have shown that leptin indirectly transactivates erbB2 and stimulates epidermal growth factor (EGF) receptor phosphorylation in tumor cells." (PMID 21533119, 2011). "After accumulation, the T cells stimulated by EGF-SEA became tumor-sensitive CTLs that secreted the tumoricidal cytokines TNF-α and IFN-γ, and the granulolytic proteins perforins and granzyme B." (PMID 21311755, 2011). "Macrophages express CSF-1 receptors and produce EGF, whereas tumour cells express EGF receptors and produce CSF-1." (PMID 22005011, 2011). "Here, the targeting of tumor-specific infiltrating CTLs was dependent on a fusion protein consisting of human epidermal growth factor (EGF) and staphylococcal enterotoxin A (SEA) with the D227A mutation." (PMID 21311755, 2011).
tumor (continued). "In order to focus our analysis on TFs whose activity can be modulated by EGF signaling, we selected motifs of TFs downstream of EGF according to network analysis and of TFs upregulated in the tumor state." (PMID 21464922, 2011). "EGF induces hyperproliferation of epidermal tissues and enhances tumor promoting actions such as proliferation and metastasis during the progression of cancer." (PMID 22087246, 2011). "It is of considerable importance, that c-Myb regulates Igf2, which allows tumor cells to develop an independent autocrine loop thereby integrating EGF and IGF-2 signaling networks." (PMID 21464922, 2011). "We additionally show that labeled EGF-SEA was directly targeted to the tumor tissue after intravenous (i.v.)injection." (PMID 21311755, 2011). "EGF stimulates the migration of tumour cells and up-regulates the production of CSF-1 which subsequently promotes migration of TAMs." (PMID 22005011, 2011). "Once the tumor formed a site for the retention of EGF-SEA proteins, it was possible for tumor-unspecific T lymphocytes including CD4+ and CD8+ T cells to be likewise retained." (PMID 21311755, 2011). "Previously, we have shown that expression of Mena and MenaINV in tumor cells sensitizes cells to stimulation by EGF during macrophage mediated in vivo invasion and transendothelial migration." (PMID 21108830, 2010). "Oral administration of abalone visceral extract significantly inhibited tumor progression by decreasing the levels of Cox-2, EGF, VEGF, and FGF in primary tumor as well as metastatic lesions." (PMID 20961430, 2010). "Metronomic gemcitabine also significantly increased apoptosis in cancer-associated fibroblasts and induced greater reductions in the tumour levels of multiple pro-angiogenic factors, including EGF, IL-1α, IL-8, ICAM-1, and VCAM-1." (PMID 20531411, 2010). "The EGF signalling network provides an array of therapeutic targets for the control of tumour growth." (PMID 20010942, 2010). "In our study, we found that the number of G0 phase cells was reduced and more tumor cells were recruited into an activated phase by EGF, while the toxicity of 5-FU was enhanced nearly threefold." (PMID 23554613, 2010). "The EGF signalling stimulates the growth of bone metastasis directly by increasing tumour cell proliferation and indirectly by engaging bone stromal cell in metastasis-promoting activities." (PMID 20010942, 2010). "Expression of pS2 is driven by a complex promoter containing a promoter/enhancer region responsive to estrogens, EGF, a phorbol ester tumor promoter, c-Ha-ras oncoprotein, and c-jun protein." (PMID 20300195, 2010). "This increase in metastasis was found to arise from increased EGF-induced invasion, tumor cell protrusion and matrix degradation activity by invadopodia." (PMID 21108830, 2010). "During tumor initiation, TAMs create a favorable environment for tumor growth by secreting epidermal growth factor (EGF), platelet-derived growth factor (PDGF), TGF-β, IL-6, IL-1, and tumor necrosis factor (TNF)-α." (PMID 21437225, 2010). "Stimulation of tumor cells with epidermal growth factor (EGF) leads to phosphorylation of serine residues 405 and 418 within the PR domain, coincident with a characteristic shift in cortactin electrophoretic mobility from 80 kDa to 85 kDa in SDS-PAGE." (PMID 21079800, 2010). "Recently, the role of EGF signalling in mediating tumour–stroma interaction in the tumour microenvironment becomes increasingly recognised." (PMID 20010942, 2010). "Molecules involved in carcinogenesis, cancer gene mutation, tumor angiogenesis and tumor signal transduction, telomerase, and growth factors such as epidermal growth factor are potential targets for tumor treatment." (PMID 20626878, 2010). "Then we stimulated tumor cells with an EGF co ncentration of 100 ng/ml for different time periods, and found that the number of G0/G1 phase cells was reduced significantly at 48 h by 10% compared to 24 h (P < 0.05)." (PMID 23554613, 2010).